CTLA4 (cytotoxic T-lymphocyte associated protein 4)
Diseases named in the same sentence as CTLA4 in open-access papers (continued):
Sharing a sentence is not in itself a finding about the gene and the disease.
tumor (continued). "Consistent with the immune suppressive effects of TGF-β, treatments with TGF-β Trap control or BA led to increased tumour-associated CD8 T cells expressing the activation marker and immune checkpoint CTLA-4." (PMID 38622286, 2024). "ICIs enhance anti-tumor responses by reducing T cell suppression, specifically targeting CTLA-4 and PD-1 pathways to increase their efficacy against tumors." (PMID 39839672, 2024). "And combining with CTLA4 blockade further augments the activation of these effector phenotype Tregs, ultimately failing to control tumor growth." (PMID 39446493, 2024). "Currently, PD1 and CTLA4 are the most studied tumor-related immune checkpoint molecules (ICPs), which have different mechanisms of action." (PMID 38903931, 2024). "Yu, Zhang, and colleagues demonstrate here that locally delivering CpG-Stat3siRNA enhances the efficacies of systemic PD-1 and/or CTLA4 blockade in two mouse tumor models and a xenograft tumor model." (PMID 39618825, 2024). "Congruently, dual checkpoint inhibition of CTLA4 and PD‐L1 had optimal tumor response when radiotherapy was administered prior to initiation of immunotherapy in a mouse model." (PMID 39526426, 2024). "The results showed that A2AR protein was positively correlated with PD-1 protein and negatively correlated with CTLA-4 protein, and was involved in tumor proliferation and metastasis." (PMID 39329710, 2024). "Anti-PD-1/PD-L1 and anti-CTLA4 have now been universally acknowledged as significant breakthroughs in tumor therapy." (PMID 38265973, 2024). "Recent research has highlighted the pivotal role of immune checkpoints, such as PD-1/PD-L1 and CTLA-4, in enabling tumor immune evasion." (PMID 39315102, 2024). "Flow cytometry analysis revealed an accumulation of tumor-infiltrating total T cells, T helper cells, T cytotoxic cells, and Tregs after treatment with 16 Gy + anti-CTLA4 relative to 16 Gy + IgG." (PMID 39199612, 2024). "All test animals were divided into four groups, control, carbon ion-irradiated unilateral hindlimb tumor, PD-L1+CTLA-4 inhibitor alone (PD-L1+CTLA 4 group), and carbon ion-irradiated unilateral hindlimb tumor coupled with PD-L1+CTLA 4 group (Comb group)." (PMID 38495488, 2024). "We found that all the unresponsive tumors showed higher levels of Foxp3, CTLA4, and Tim3 than responsive tumor tissues." (PMID 39128094, 2024). "They demonstrated increased tumor-specific uptake of 64Cu-DOTA-anti-CTLA-4, compared to tumor uptake of Cu64 labeled isotype control, demonstrating specificity." (PMID 39104861, 2024). "In PDAC, Galunisertib combined with dual immune checkpoint inhibitors (anti-PD-L1 and CTLA-4) significantly inhibits tumor growth and induces the infiltration of antitumor M1 macrophages." (PMID 39534084, 2024). "These involve developing ICIs including monoclonal antibodies (mAbs) to block the immunosuppressive molecules and to improve the cytotoxicity of tumor-infiltrating lymphocytes such as CTLA4, PD1, and PD-L1." (PMID 38715072, 2024). "Co-treatment of anti-TGFβ mAbs with anti-CTLA4 mAbs significantly reduced the tumor progression compared to treatment with anti-CTLA4 alone." (PMID 38891044, 2024). "With a higher affinity for the ligands CD80 and CD86 on antigen-presenting cells (APCs) than the co-stimulation receptor CD28 on T cells, the interaction between CTLA4 and its ligands suppresses T-cell activity, thereby promoting tumor growth." (PMID 39198311, 2024). "PD-1 inhibitor blocks both PD-L1 and PD-L2, whereas PD-L1 inhibitor also blocks the binding to CD80 which releases CTLA-4-mediated anti-tumor immunity." (PMID 38384808, 2024). "This treatment has been combined with other chemotherapies such as dacarbazine and anti-CTLA-4 to improve tumor responses." (PMID 39682188, 2024). "In cancer cells, the expression of CTLA4 is induced to evade T cell antitumor activity, and its blockade potentiates active immune responses against tumor cells and decreases immunosuppression by Tregs." (PMID 38542199, 2024).
tumor (continued). "Parallel studies of anti-CTLA4 therapy have indicated that antibiotics suppress the anti-tumor effects produced by ICIs." (PMID 38617537, 2024). "CTLA-4 blockade depends on several factors including Treg cells, T-cell infiltration, CD8 + T-cell activation, and tumor-associated macrophage (TAMs) recruitment." (PMID 38956700, 2024). "It has been shown that the CD80 surface molecule preferentially engages with the inhibitory protein cytotoxic T-lymphocyte associated protein 4 (CTLA4) on T-lymphocytes, leading to immune exhaustion and tumor growth." (PMID 38891044, 2024). "Our studies have shown that chronic HS diets upregulated the expression of CTLA4 in tumor-infiltrating CD8+ and CD4+T cells in both murine models." (PMID 38891044, 2024). "Recent studies have identified that LAG-3, along with PD-1 and CTLA-4, is a common receptor of nodal immune checkpoint, participating in tumor immune response and tumor immune escape." (PMID 39252941, 2024). "CD14 + CTLA-4+ tolerogenic DCs are a regulatory DC subtype that can suppress the anti-tumor immune response of CTLs via IL-10 and indoleamine-2,3-dioxygenas." (PMID 38791916, 2024). "The differential expression of immune checkpoint molecules, such as PD-L1 and CTLA-4, suggested potential immune evasion strategies employed by the tumor to evade immune surveillance." (PMID 38356715, 2024). "We treated 4662 tumor-bearing mice with a single dose of gemcitabine (G) and/or nab-paclitaxel (A), seven doses anti-PD-1 Ab (P) and/or three doses of anti-CTLA-4 Ab (C) every three days, and one dose of agonistic anti-CD40 Ab (F)." (PMID 38378697, 2024). "Eosinophils infiltrated into the tumor after administration of the anti-CTLA-4 Ab, but depletion of eosinophils by anti-CD193 Ab treatment did not cancel the anti-tumor effect of the anti-CTLA-4 Ab." (PMID 39106430, 2024). "In most cancers, highly CTLA-4-expressing Fr.II eTregs are the predominant tumor-infiltrating Foxp3+Tregs." (PMID 39290699, 2024). "In the TME of HNSCC, Treg cells regulate the expression of CTLA-4 on their cell surface to suppress anti-tumor immunity." (PMID 38294629, 2024). "The depletion of Treg cells in the TME using anti-CTLA-4 mAbs with antibody-dependent cell-mediated cytotoxicity (ADCC) activity is a key mechanism for achieving tumor regression." (PMID 38791528, 2024). "Enhanced CTLA-4 expression further impedes anti-tumor immune responses by competing with CD28 for B7 molecules, thereby reducing T cell activation and proliferation." (PMID 38415252, 2024). "Research studies have demonstrated encouraging results in the use of DC-tumor fusion vaccines for various types of cancer by blocking CTLA-4." (PMID 38462628, 2024). "In multiple preclinical models, vitamin C, together with anti-PD-1 and anti-CTLA-4, induced apparent tumor growth inhibition or regression." (PMID 39451738, 2024). "HIF-1α induces the expression of several immune checkpoint molecules, including PD-L1 and CTLA-4, on tumor cells and immune cells, respectively, thereby inhibiting T cell activation and promoting an immunosuppressive environment." (PMID 39457484, 2024). "We observed an enhanced anti-tumor response, which led to a delay in tumor growth and, in some cases, a complete elimination of tumors when combining IR with anti-CTLA4." (PMID 39199612, 2024). "Strikingly, a significant tumor growth delay and complete cure in one-third of the mice were seen with the combination of IR and anti-CTLA4." (PMID 39199612, 2024). "Host MPO deficiency significantly reduced both CD11b+Ly6G+ myeloid cells, macrophages (CD11b+F4/80+) and exhausted CD4+PD1+CTLA4+ T cells within the tumor microenvironment." (PMID 38367056, 2024). "One of the most important features of ‘immune hot tumours’ is the activation of immune checkpoints including PD-1, CTLA-4, and lymphocyte activation gene 3 (LAG3)." (PMID 38461439, 2024).
tumor (continued). "In contrast, the LR subtype consists of a more homogenous lymphocyte background, suggesting a less suppressed immune response, scarce tumour cells, and better prognosis, as reflected by lower CTLA-4 expression." (PMID 38978137, 2024). "It has also been reported that the administration of anti-CTLA-4 in patients with metastatic melanoma has shown a durable tumor immune response in phase I and phase II clinical studies through CD28–B7-mediated Treg cell activation against TAA." (PMID 38255322, 2024). "While previous studies have predominantly focused on the role of CTLA4 in immune cells, emerging evidence suggests its level in tumor cells as well." (PMID 38398223, 2024). "For example, by pre-testing tumor samples for specific phenotypes and functional states of immune cells, doctors can predict the patient’s responsiveness to PD-1/PD-L1 or CTLA-4 inhibitors, thus selectively choosing the treatment method most likely to benefit." (PMID 39539544, 2024). "By blocking the CTLA-4 signalling pathway, the inhibitory state of T cells can be lifted and the anti-tumour immune response can be enhanced." (PMID 39474352, 2024). "Tumor cells inhibit the function of T cells by activating the PD-1/PD-L1 and CTLA-4 signaling pathways to avoid being recognized and cleared by the immune system." (PMID 39741315, 2024). "In conclusion, in a model of lymphocyte-depleted cancer that favors myeloid and Treg infiltration, we reveal that CTLA-4 and PD-1 blockade had the opposite effect on RT-induced tumor control compared with immunogenic tumors with high Tconv infiltrates." (PMID 38349740, 2024). "Targeting tumor immune checkpoints, such as programmed cell death protein 1 ligand (PD-L1) and cytotoxic T lymphocyte antigen 4 (CTLA-4), holds great promise for oncology treatment, particularly in combating glioma immune evasion." (PMID 38613802, 2024). "By blocking the binding of CTLA-4 to its ligands, T cell activation and anti-tumor immune responses are enhanced." (PMID 39669560, 2024). "In conclusion, by using this liver tumor cell transplantation model, we demonstrated that anti-CTLA-4 Ab exhibits anti-tumor effects via the Th1/IFN-g axis." (PMID 39106430, 2024). "Immune checkpoint inhibitors (ICIs), which specifically target CTLA‐4 and PD‐1/PD‐L1, have demonstrated the potential to restore immune cell activity against tumor cells and mitigate immune evasion." (PMID 38566277, 2024). "Anti–CTLA-4 therapy is capable of depleting Tregs in mouse tumor models and some human tumors, and while this is thought to be one of the major mechanisms of anti–CTLA-4 efficacy in mouse models, its role in human tumors is less clear." (PMID 39561007, 2024). "Instead of using anti-CTLA4, probiotics have emerged as a potential option to be combined with anti-PD-1 for tumor immunotherapy." (PMID 39456702, 2024). "We found that the combination therapy modulates many tumor-infiltrating cell populations, especially T cell and macrophage populations, compared with anti-CTLA-4 treatment alone." (PMID 38517331, 2024). "Using CT26 murine colorectal tumor xenografts, they compared tumor responses with treatment across three doses of anti–CTLA4 and anti–PD-L1 antibodies each." (PMID 39850874, 2024). "Overall, combining OVs with CTLA4 inhibitors enhances immune-mediated tumor destruction, offering a promising future for cancer treatment." (PMID 39684701, 2024). "We assessed combinatorial treatments in MC38 tumor bearing mice by choosing an injection dose of cells and treatment schedule where monotherapy with anti-CTLA-4, anti-PD-1, or neo VAX alone is largely ineffective." (PMID 38187708, 2024). "For both tumor models, the combination of α-PD-1 and α-CTLA4 resulted in the most significant differences in CD8 signal when comparing responders and non-responders." (PMID 38918836, 2024).
tumor (continued). "After oral administration of Bacteroides spp., the antitumor efficacy of the anti-CTLA-4 inhibitor was restored, with an increase in intratumoral mature DCs and an increase in the Th1 response in tumor-draining lymph nodes." (PMID 38558812, 2024). "In NSCLC, CTLA-4 positivity was identified on tumor epithelial cells as well as on tumor stromal compartments with relatively homogenous distribution." (PMID 38384472, 2024). "When CTLA4 is overexpressed, the inhibitory signals produced exceed the immunogenicity provided by tumor cell surface antigens, downregulating or terminating T-cell activation, leading to immune escape of the tumor." (PMID 39464701, 2024). "Studies from other laboratories have shown that CD80 expression on TISCs in the context of CTLA4 on immune cells results in a blunted effector anti-tumor response and promotes tumor progression." (PMID 38891044, 2024). "The presence of circulating MDSCs mainly correlates to the tumor stage, as described by recent research investigating the interplay between tumor stage, PD-1, and CTLA4." (PMID 39766202, 2024). "Staining using serial sections of HGSOC showed that PD-L1, VISTA, and CTLA4 were expressed in tumor cells and TILs." (PMID 38634058, 2024). "Counterintuitively, antibody-mediated blocking of the coinhibitory receptors CTLA-4 or PD-1 further increased this Treg response and antagonized tumor regression." (PMID 38349740, 2024). "Combined immunotherapy targeting PD-L1 and CTLA-4 has shown enhanced activity in several tumor types." (PMID 36639648, 2023). "It is well known that cytotoxic T-lymphocyte-associated protein 4(CTLA-4) and programmed death 1 (PD1)/programmed cell death-Ligand 1(PD-L1) have been demonstrated to be important checkpoints that block anti-tumor immune responses." (PMID 37926757, 2023). "CTLA-4 promotes tumor immune evasion by competitively binding to B7 ligands and inhibiting the function of Treg cells." (PMID 36798129, 2023). "Tumor cells use this negative regulation to evade human immune surveillance by interfering with CTLA-4, PD-1, and PDL-1 immune checkpoints." (PMID 37915064, 2023). "Tumor-bearing mice were given a single i.t. injection of mANK-101 alone or combined with PD-1 or CTLA-4 blockade starting either simultaneously (concurrent) or 1 week after (sequential) mANK-101 injection." (PMID 38063196, 2023). "In contrast to activated T cells expressing CTLA-4 after activation, regulatory T (Treg) cells constitutively express CTLA-4 and play a significant role in tumor tolerance through surface/intracellular CTLA-4 and its soluble counterpart." (PMID 37197667, 2023). "PD-1 and CTLA-4 appear to have an effect on glycolysis of tumor cells, and thereby on the ability of immune cells to perform glycolysis due to nutrient competition within the TME." (PMID 36874131, 2023). "Surprisingly, preclinical and clinical findings demonstrated that PD-1 × CTLA-4 bsAbs have stronger anti-tumor activity compared to combination therapy, with manageable irAEs38,39." (PMID 36971124, 2023). "First, inhibition of CTLA-4 enhances early activation and proliferation of effector T cells upon tumor neoantigen recognition in the lymph nodes." (PMID 35864269, 2023). "They reported that dual blockade of PD‐L1 and CTLA‐4 significantly augmented the anti‐tumor effect of the CSC‐DC vaccine." (PMID 37698048, 2023). "In vivo experimentation was conducted with KPCA.B cells to identify a potential benefit in combining 5-aza, givinostat (HDACi), and ICB (PD-L1/CTLA-4) in syngeneic HGSOC tumor models that recapitulate the clinical disease and ICB responses." (PMID 37627156, 2023). "Blocking the interaction of CTLA-4 with CD80/CD86 led to tumor shrinkage and improvement in survival in pre-clinical GBM models." (PMID 37046685, 2023).
tumor (continued). "In contrast, the combination of N1, FSL-1, R848, and anti-CTLA4 (TheraVacplus) further increased tumor-infiltrating leucocytes, CD4+ T cells and CD8+ T cells, effector/memory T cells, and markedly lowered fractions of tumor-infiltrating cDCs and pDCs." (PMID 37190294, 2023). "Using a cutoff expression of 10% cells, it was observed that patients with higher Ann Arbor stage (II/III/IV) had CTLA-4 expression in more than 10% of the immune cells within the tumor microenvironment, which was statistically significant." (PMID 37305822, 2023). "Recent studies have demonstrated that PD-1 and CTLA-4 expressed in T cells in the tumor environment also have soluble forms (sPD-1 and sCTLA-4) in peripheral blood." (PMID 37887315, 2023). "A significant synergistic therapeutic effect with ALT-803 was also reported to boost the tumor response to anti-CTLA-4 checkpoint blockade therapy." (PMID 36829496, 2023). "The combination of intratumoral G47Δ and systemic anti-CTLA-4 antibody was shown to recruit effector T cells into the tumor efficiently while decreasing regulatory T cells." (PMID 37491263, 2023). "The use of anti-CTLA-4 antibody prevents T cells from being inhibited, enabling them to better identify and attack tumor cells." (PMID 37860188, 2023). "One potential advantage of using BsAbs is that they can be designed to selectively bind to cells expressing both PD-1 and CTLA-4, which are mainly tumor-infiltrating lymphocytes (TILs)." (PMID 37441075, 2023). "The combination of DSF/MS-Cu and anti-CTLA–4 antibody further inhibited tumor growth, showing the synergistic effect of DSF/MS-Cu and immune checkpoint inhibitors." (PMID 38133040, 2023). "This approach has been exploited for the development of the bispecific antibody MEDI5752 enabling PD1 blockade and the preferential neutralization of CTLA4 on tumor-infiltrated PD1+ antigen-experienced T-cells, compared to PD1- T-cells." (PMID 37189383, 2023). "Preclinical trials have demonstrated that radiotherapy can convert tumours unresponsive to CTLA-4 into responsive tumours." (PMID 38259489, 2023). "Comparing to free anti-CTLA-4 antibody + Doxil, CTLA-4 PEG-liposomes (modification of liposomes by covalent conjugation with PEG) + Doxil showed even better tumor inhibition and survival rate." (PMID 37106400, 2023). "In the treatment experiment with anti-PD-1 together with anti-CTLA-4 versus control (saline), we observed a slightly higher signal at day 7 in the tumor of the treated versus the control but from day 11 the signals in the treated versus control were similar." (PMID 37497236, 2023). "For example, the measured level can be used to determine the threshold of CTLA4 copies and/or the ratio of CD28 to CTLA4 required for the activation of CD8+ cytotoxic T cells for subsequent tumor killings." (PMID 37110545, 2023). "Clear cell renal cell carcinoma (ccRCC) is a highly inflamed and immune-infiltrated tumor type with high expression of immune checkpoints, such as PD-L1 and CTLA-4." (PMID 37842234, 2023). "CT26 subcutaneous inoculation model mice treated with DSP-0509 5 mg/kg i.v. weekly combined with anti-CTLA-4 antibody 200 μg i.p. twice weekly showed significant tumor growth inhibitory activity compared to the vehicle and anti-CTLA-4 antibody treated groups." (PMID 36793737, 2023). "The observed differences in immune checkpoint proteins like PDL1 and CTLA4 indicate greater impedance of anti-tumor immunity in the high AMPAO group, consistent with prior studies linking PDL1 expression to poor prognosis and immunotherapy response in HNSCC." (PMID 37897503, 2023). "The present work also investigated KRAS and CTLA-4 mRNA expression in CTCs and matched primary tumour tissues." (PMID 37761948, 2023). "Conversely, blocking CTLA-4 increased the number of T effector cells in the tumor microenvironment of BCs." (PMID 36900322, 2023).